HK2P1 (hexokinase 2 pseudogene 1)
Synonyms: formerly HK2P
Gene: Processed pseudogene on chromosome X (80,571,871 to 80,574,607, reverse strand). Ensembl gene ENSG00000228612.
Diseases named in the same sentence as HK2P1 in open-access papers:
HK2P1 is named in the same sentence as 1 disease in open-access papers, as found by Europe PMC text mining. Sharing a sentence is not in itself a finding about the gene and the disease. The quoted sentences say what the papers report.
preeclampsia (2 papers, 2018 to 2022). Preeclampsia is a hypertensive disorder of pregnancy that is characterized by new-onset hypertension with proteinuria presenting after 20 weeks of gestation, and depending on mild or severe forms may initially present with severe headache, visual disturbances, and hyperreflexia. "For example, the HK2P1 pseudogene may contribute to preeclampsia by acting as a competing endogenous RNA for hexokinase 2 and impairing decidualization." (PMID 35629146, 2022). "HK2P1 is a lncRNA found to be decreased in the decidua of severe preeclampsia patients." (PMID 30322386, 2018).